XPR1 (xenotropic and polytropic retrovirus receptor 1)
Diseases named in the same sentence as XPR1 in open-access papers (continued):
Sharing a sentence is not in itself a finding about the gene and the disease.
tumor (10 papers, 2011 to 2025). "To our knowledge, we were the first to discover that XPR1 can regulate autophagy and tumor immunity and that XPR1 regulates tumor immunity through the lysosomal protein LAMP1." (PMID 40641524, 2025). "RBM15 knockdown impedes tumor growth via XPR1 regulation, underscoring the oncogenic role of the RBM15/XPR1 axis in LUAD." (PMID 41403702, 2025). "Next, we performed immunohistochemistry assays to detect the effects of IGF2BP3/circGNB1/miR-515-5p/miR-582-3p/XPR1/IL6 axis on tumor tissues." (PMID 37407973, 2023). "Strikingly, tumors formed by XPR1 knockdown SCC25 cells grew much more slowly than scramble-transduced control SCC25 cells as indicated by the tumor volumes and weights." (PMID 30995931, 2019). "Third, how does binding of envelope protein to XPR1 or alternative receptor on tumor cells induce production, and/or release of soluble factors that disrupt tumor vascular maturation?" (PMID 23537062, 2013). "Silencing XPR1 combined with chloroquine significantly inhibited the growth of tumor lesions." (PMID 40641524, 2025). "XPR1 is involved in tumor cell growth, metastasis, and invasion." (PMID 40641524, 2025). "Our findings suggest that targeting XPR1 could represent a novel therapeutic approach for treating HNSC, offering the possibility of disrupting critical phosphate pathways that sustain tumor growth and progression." (PMID 39335197, 2024).
infection (9 papers, 2009 to 2024). The state of being infected such as from the introduction of a foreign agent such as serum, vaccine, antigenic substance or organism. "We propose a scenario of frequent selective sweeps in Xpr1, possibly due to an ongoing co-evolution between receptor variants and bursts of infections, complemented by an introgression of receptor variants that convey resistance from other populations." (PMID 26555287, 2015). "Accordingly, the currently available data suggests that there is functional variation among Xpr1 alleles and that this could play an important role in the adaptation of mice to infections by XP-MLVs." (PMID 26555287, 2015). "We therefore monitored PFBC XPR1/SLC53A1 variants for their capacity to serve as cell surface receptor for X-MLV entry and infection." (PMID 31043717, 2019). "XPR1 mediates infection of cells by both polytropic (P-) and xenotropic (X-) MLVs in a variety of hosts." (PMID 26555287, 2015). "In addition, Xpr1 can only inhibit infection by exogenous retroviruses but cannot prevent the same viral lineages from being inherited as ERVs." (PMID 26282858, 2015). "Three of the four XPR1 variants of Mus supported replication of XMVs; only Xpr1n of the laboratory mouse strains failed to mediate infection of any of these viruses." (PMID 19811656, 2009). "The results were unrelated to variation in the major MLV receptor Xpr1, which can restrict exogenous MLVs, suggesting that endogenous MLV distribution reflects gene flow unrelated to exogenous infection." (PMID 26282858, 2015). "The discord between the MLV tropism determining Xpr1 gene haplotypes and MLV distribution suggests that gene flow plays a more important role in MLV genomic colonization in mice than infection." (PMID 26282858, 2015). "These classes include the ecotropic viruses, limited to rodents (mCAT1 receptor), xenotropic viruses (excluded from infection of inbred mice; Xpr1 phosphate exporter receptor), and polytropic/mixed polytropic viruses, infecting mouse and nonrodent species using Xpr1 as their receptor." (PMID 31815961, 2019). "This scenario is in line with our finding that overexpression of XPR1 in 293 and CHO cells did not significantly increase the cell-cell fusion activities of XMRV Env truncation mutants despite their increased infection in these cells (data not shown)." (PMID 22479434, 2012). "In this case, either this interaction is not essential for successful infection of murine cells or VR3 loops containing arginine and threonine can only bind to the murine Xpr1." (PMID 20137084, 2010). "The results did not correlate with variation in the major MLV receptor Xpr1, which can restrict exogenous MLVs, suggesting that endogenous MLV distribution may reflect gene flow more than past resistance to infection." (PMID 26282858, 2015).
cancer (7 papers, 2016 to 2024). A tumor composed of atypical neoplastic, often pleomorphic cells that invade other tissues. "In addition, the upregulation of XPR1 has been implicated in several cancers, facilitating cancer proliferation, migration, and invasion." (PMID 39711567, 2024). "Given the emerging understanding of phosphate transport in cancer biology, it is imperative that research into the development of XPR1 inhibitors rapidly advances." (PMID 39335197, 2024). "This is in line with previous studies in other malignancies, whereby the impairment of miR-214-5p by competitor endogen RNAs (e.g. DANCR, LINC00963 and circ-XPR1) promotes cancer cell proliferation and metastasis." (PMID 34113568, 2021). "The molecular mechanism by which XPR1 helps to cancer progression was investigated by luciferase reporter activity, ELISA, PKA activity assay, immunofluorescence, western blotting and qPCR assay." (PMID 30995931, 2019). "XPR1 is a known oncogene which plays vital roles in various cancers." (PMID 37407973, 2023). "To investigate the role of XPR1 in cancer, we first analyze its expression." (PMID 30995931, 2019). "However, the clinical significance and biological roles of XPR1 in cancer progression remain largely unknown." (PMID 30995931, 2019). "XPR1 and KIDINS220 have recently been shown to form a complex that is required for normal regulation phosphate efflux in certain cancer cells." (PMID 37872410, 2024). "Here, we demonstrate for the first time the potential role of XPR1 in TSCC progression and the potential value as a novel therapeutic target in human cancer." (PMID 30995931, 2019). "From a subset of gene products found upregulated on the surface of MCF10A-KRasG12V, the xenotropic and polytropic retrovirus receptor 1 (XPR1) from the formation of cellular protrusions network and the vang-like protein 1 (VANGL1) from the cancer network were selected for cross-validation." (PMID 27894102, 2016). "Understanding the precise roles of XPR1 in the pathogenesis and progression of TSCC and activation of the NF-κB signaling pathway will increase our knowledge of the biological basis of cancer, and might enable the development of novel therapeutic strategies against TSCC." (PMID 30995931, 2019). "While the involvement of XPR1 in the biology of KRas-driven cancers has not been previously reported, it is plausible to hypothesize that its downstream upregulation may be involved in the regulation of cell proliferation." (PMID 27894102, 2016). "However, the clinical role of XPR1 in human cancers has not yet been characterized." (PMID 30995931, 2019). "However, the role of XPR1 in human cancers has not yet been characterized." (PMID 30995931, 2019).
XPR1 also shares sentences with these, for which no sentence is quoted: movement disorder (2 papers); viral infection (2); adenocarcinoma (1); Basal ganglia calcification (1); bipolar disorder (1); breast carcinoma (1); chronic headaches (1); chronic kidney disease (1); Cognitive impairment (1); colorectal cancer (1); epilepsy (1); generalized dystonia (1); Glucose Metabolism Disorder (1); heart failure (1); hepatocellular carcinoma (1); hypertriglyceridemia (1); hypophosphatemia (1); hypophosphatemic rickets (1); inflammatory bowel disease (1); migraine (1); myopathy (1); nasopharyngeal carcinoma (1); Obesity (1); Parkinsonism (1); primary biliary cholangitis (1); Type 2 diabetes (1).